INS (insulin)
Diseases named in the same sentence as INS in open-access papers (continued):
Sharing a sentence is not in itself a finding about the gene and the disease.
diabetes (continued). "Sliding-scale and basal-bolus insulin regimens are two options available for the treatment of severe or acute hyperglycemia in type 2 diabetes mellitus patients." (PMID 25181406, 2014). "Diabetes mellitus (DM) is a group of metabolic diseases characterized by high levels of blood sugar, which are due to problems in insulin secretion or insulin, or both." (PMID 25232702, 2014). "First phase insulin secretion and post-prandial hyperglycemia are early signs of diabetes in people from Asia." (PMID 24552366, 2014). "We also provide data implicating defective glutamate signaling in the pathophysiology of insulin secretion in the GK and ZF rat models of human diabetes and obesity, respectively." (PMID 25373904, 2014). "Diabetes accelerates aging in the brain and alters vascular reactivity through the combined effects of central insulin resistance on microvasculature, brain metabolism, glucose utilization, and neuronal survival." (PMID 25018729, 2014). "On the contrary, a higher educational level, treatment by an internist, using insulin, polypharmacy, better diabetes knowledge, and more hyperglycemic episodes were less likely to be associated with not using the Web portal." (PMID 25424228, 2014). "Regular exercise can improve cardiovascular function, as well as other diabetes‐related complications including bone health, body composition, kidney function, insulin sensitivity, and overall quality of life." (PMID 25413321, 2014). "Active compound or an amalgam active compounds of in B. monosperma have strong potential in treating both types 1 and 2 diabetes by enhancing quality and quantity of insulin secreted and by enhancing hepatic glucose utilization." (PMID 24860609, 2014). "Computer-assisted decision support is an emerging modality to assist patients with type 2 diabetes mellitus (T2DM) in insulin self-titration (ie, self-adjusting insulin dose according to daily blood glucose levels)." (PMID 25340869, 2014). "The proposed predictive factors for remission and other outcomes includes age, diabetes duration, insulin reserve& requirement, body mass index (BMI), ethnicity and number of preoperative medications required to manage blood glucose." (PMID 25426451, 2014). "Diabetes is a chronic disease that occurs either when the pancreas does not produce enough insulin or when the body cannot effectively use the insulin it produces." (PMID 25162051, 2014). "Based on the area under the receiver operating characteristic curve, cut-off values of 19 units for daily insulin dose and nine years for duration of diabetes were identified." (PMID 24578756, 2014). "The pivotal role p38δ MAPK plays in integrating insulin secretion and survival of pancreatic β cells makes it an attractive potential therapeutic target for the treatment of human diabetes." (PMID 25313309, 2014). "Hypoglycemia is one of the main factors for patients with diabetes requiring insulin to achieve tight glycemic control and a reduced likelihood of complications." (PMID 25187822, 2014). "The study of the cognitive status of 16596 women aged between 70 and 81 years old indicated that the risk of experiencing cognitive decline in women with type 2 diabetes was increased with insulin use and the duration of diabetes." (PMID 24495364, 2014). "We have previously shown that excision of the Men1 gene ameliorated pre-existing hyperglycemia and increased both glucose-stimulated insulin release and circulating insulin levels in mouse diabetes models." (PMID 25594065, 2014). "The controls were 10 pregnant women with type 1 diabetes matched for age, history of diabetes, and expertise with self-monitoring and insulin regimens." (PMID 25295059, 2014). "Current treatments for diabetes include the use of exogenous insulin and the administration of allopathic drugs, such as sulfonylureas (glibenclamide), biguanides (metformin), and alpha-glucosidase inhibitors (acarbose and miglitol)." (PMID 24872834, 2014).
diabetes (continued). "Diabetes mellitus is a pathological condition which results in severe metabolic imbalances and is characterized by high blood glucose level, low blood insulin level or insensitivity of target organs to insulin." (PMID 24991800, 2014). "The mainstay of type 1 diabetes mellitus (T1DM) treatment consists of subcutaneous (SC) insulin administration using multiple daily injections (MDI) or continuous subcutaneous insulin infusion (CSII) with an externally placed pump." (PMID 24708696, 2014). "These cases suggest that acute NKHG should not be delayed as a possible etiology of chorea-ballismus and seizures in elderly, given that diabetes is usually longstanding and poorly controlled and the variable response of elderly diabetics to insulin therapy." (PMID 25422738, 2014). "Continuous intraperitoneal insulin infusion (CIPII) with an implantable pump is a treatment option for patients with type 1 diabetes mellitus (T1DM)." (PMID 24708696, 2014). "Using insulin-deficient diabetic mice model, in vivo experiments demonstrated that FXR activation ameliorated insulin secretion and delayed development of signs of diabetes, hyperglycemia, and glycosuria." (PMID 24872814, 2014). "MDI therapy for diabetes requires bolus injections of rapid or short-acting insulin prior to each meal and a long-acting insulin injection once or twice per day for basal insulin coverage." (PMID 25187822, 2014). "For example, the individuals with ketosis-onset diabetes are able to maintain optimal glycemic control on oral antidiabetic agents after recovering from the initial crisis with insulin therapy." (PMID 24926320, 2014). "Compared with control littermates, the number of insulin granules was considerably reduced in mice exposed to diabetes for 4 weeks." (PMID 25145789, 2014). "Diabetes is a chronic metabolic disease characterized by hyperglycemia due to defective insulin secretion, insulin action, or both." (PMID 25497096, 2014). "BMI-SDS did not correlate strongly or significantly with age, duration of diabetes, insulin dose, or HbA1c levels (r from −0.007 to 0.093, all P values >0.05)." (PMID 25214838, 2014). "Diabetes mellitus is diagnosed on the basis of elevated blood glucose, despite significant changes in other blood markers, such as lipids, lactate, or insulin." (PMID 24949486, 2014). "About 66% of the students assumed that sugar cannot “move” in the blood with diabetes and 56% thought that all patients with diabetes must take insulin injections." (PMID 25360161, 2014). "The effect of Perk gene dosage on glucose homeostasis is amplified in combination with the dominant Akita insulin mutant, which progressively develops diabetes postnatally." (PMID 24915520, 2014). "It is mainly classified into type 1 diabetes and type 2 diabetes, and 90∼95% diabetic patients are type 2 diabetes mellitus, which is characterized by insulin resistance that results from the decrease in insulin action on target tissues." (PMID 24918756, 2014). "The same interaction between DR, insulin therapy and diabetes duration was significant when adding treatment satisfaction for explaining the variability observed in the quality of life assessment." (PMID 25138117, 2014). "Diabetes results from pancreatic inability to secrete the insulin needed to overcome this resistance." (PMID 24886809, 2014). "Downregulation of this gene was found in rodent models of diabetes and was reported to impair insulin signaling in the muscle and induce oxidative stress; hence it was proposed as major regulator of metabolic flexibility of skeletal muscle." (PMID 25403085, 2014). "Dramatic changes in insulin content, islet morphology and β-cell ultrastructure were evident after 4 weeks of diabetes." (PMID 25145789, 2014). "The mice initially developed diabetes due to impaired glucose-stimulated insulin secretion just as we saw in our model, but as the animals aged there was a concurrent decrease in beta cell mass that sustained the diabetes phenotype." (PMID 25532126, 2014).
diabetes (continued). "In Australia the main health professional groups involved in insulin initiation are specialist physicians, specialist diabetes nurse educators (DNEs) and general practitioners (GPs)." (PMID 25361788, 2014). "Type-2 diabetes mellitus is a chronic metabolic disorder that results from defects in both insulin secretion and insulin action." (PMID 24991576, 2014). "The hope is that patients, their relatives, and students can learn how to balance insulin and diet in diabetes by modifying the simulations." (PMID 24511312, 2014). "Of the 13 678 (84.6%) participants with self‐reported diabetes with dataavailable on hypoglycaemic medication use, 76.9% reported taking such medication (84.7% oralhypoglycaemics; 18.9% insulin)." (PMID 24344928, 2014). "Diabetes was induced using multiple streptozotocin injections (5×; 20 mg/kg) while subcutaneous insulin pellets maintained glycemia in a range typical for individuals that exercise with T1DM." (PMID 25413321, 2014). "Discovery of Drosophila mechanisms and regulators controlling in vivo insulin dynamics should accelerate functional dissection of diabetes genetics." (PMID 25101872, 2014). "The measurement of serum C-peptide provides an accurate assessment of residual beta-cell function and thus has been widely used as a marker of insulin secretion in patients with diabetes." (PMID 25945127, 2014). "Continuing an insulin regimen with post-GB patients with type 1 diabetes is critical in order to prevent onset of diabetic ketoacidosis, and frequent postoperative follow-up for adjustment of prandial insulin requirements is absolutely required." (PMID 24668543, 2014). "Sprague-Dawley rats were divided into 3 groups, normal (NG), diabetes (DG) and diabetes with insulin-treatment (TG)." (PMID 25289023, 2014). "This association did not remain after additional adjustment with ΔC-peptide in the regression model, indicating that insulin secretory function played a major role in this close relationship between GA and duration of diabetes." (PMID 25265016, 2014). "A simplified explanation can be that inflammation increases insulin resistance, which in turn leads to obesity while perpetuating diabetes, high blood pressure, prothrombotic state and dyslipidaemia." (PMID 24571954, 2014). "Diabetes is a metabolic disorder characterized by chronic hyperglycemia as a result of defects in insulin action, insulin secretion, or both." (PMID 24872834, 2014). "On the other hand, studies suggest that in patients suffering from diabetes, higher fat meals acutely increase the glucose concentration and the requirement for insulin compared with meals containing similar carbohydrate but lower fat contents." (PMID 25222490, 2014). "The expression of Pgc1α in islets was also reported to be elevated in several animal models that have increased demand for insulin secretion such as ob/ob mice, mice after partial pancreatectomy, and Zucker Diabetic Fatty (ZDF) rats." (PMID 24505268, 2014). "The mean diabetes duration of over 8 years at baseline also suggests delayed insulin initiation in this study population." (PMID 25048824, 2014). "Glycemic clamps are the gold standard technique to assess both insulin sensitivity and insulin secretion in humans and animal models of diabetes." (PMID 24594704, 2014). "Insulin secretion from pancreatic β-cells is critical for proper maintenance of blood glucose levels, with perturbations to this process leading to diabetes." (PMID 25310693, 2014). "Of note 88.6% of participants were on a statin and 40% were taking insulin.The mean HbA1c and the mean duration of diabetes were 7.4 ± 0.7 and 11.2 ± 9 years, respectively." (PMID 25057411, 2014). "The competition successfully produced six submitted and developed apps: Diabetes Logger, Diabetes Health Tracker, Insulin Calc, cpSlider, T1NDA and You + Your Diabetes." (PMID 25654312, 2014).
diabetes (continued). "Comparison of SFRP4 concentrations between strata of categorical variables showed that SFRP4 levels were higher in patients with metabolic syndrome, insulin therapy, diabetes and a history of myocardial infarction or PCI." (PMID 25408147, 2014). "Diabetes duration was actually much higher for most individuals because the mean time between coming under observation and first insulin prescription was 4±2 years." (PMID 24667573, 2014). "Several factors contribute to this, chief among which is insufficient knowledge of insulin and diabetes management on the part of health care providers and patients leading to errors in insulin therapy." (PMID 24397956, 2014). "It appeared to be more difficult to live with diabetes than earlier and new questions in relation to management and adjusting medication were experienced, “I was unsure, Have I taken too little insulin or too much." (PMID 25030359, 2014). "Especially, regulation of sugar metabolism is a very important role of insulin because defect in insulin action is related to type 2 diabetes mellitus." (PMID 25089832, 2014). "In this study, we have utilized one of the most widely used animal models of human disease, where diabetes is induced by selective destruction of the insulin-producing B-cells of the pancreas with a single, rapid injection of STZ." (PMID 25014552, 2014). "In insulin-resistant states (obesity, pre-diabetes, and type 2 diabetes), hepatic production of glucose and lipid synthesis are heightened in concert, implying that insulin deficiency and insulin excess coexists in this setting." (PMID 25486190, 2014). "Glucokinase activators are being investigated as potential diabetes therapies because of their effects on hepatic glucose output and/or insulin secretion." (PMID 24533087, 2014). "Diabetes originates from impaired insulin action in target tissues followed by inadequate insulin secretion." (PMID 24643026, 2014). "Type 1 diabetes mellitus (T1D) is a multifactorial autoimmune disease, in which insulin-producing beta (β) cells are ablated by the immune system." (PMID 24478773, 2014). "Diabetes is a group of metabolic diseases characterized by hyperglycemia resulting from defects in insulin secretion, insulin action, or both." (PMID 25050121, 2014). "The increase in serum and urine ACE2 activity was normalized by insulin administration at the early and late stages of diabetes in Diabetic mice." (PMID 24400109, 2014). "Type 2 diabetes mellitus (T2D) is characterized by hyperglycemia as a result of impaired insulin secretion, insulin resistance in peripheral tissues and/or increased glucose output by the liver." (PMID 25491720, 2014). "Diabetes mellitus (DM) is a metabolic disease characterized by hyperglycemia resulting from a defect in insulin action and/or production." (PMID 25197655, 2014). "IL-1 induces apoptosis in insulin-producing pancreatic β-cells, and the administration of Ana in patients with type 2 diabetes mellitus improves β-cell function." (PMID 24490798, 2014). "Metformin (MET) therapy exerts positive effects improving glucose tolerance and preventing the evolution toward diabetes in insulin resistant patients." (PMID 24884495, 2014). "Multiple regression analysis with Δweight as the dependent variable indicated that Δweight at 24 weeks of liraglutide administration was higher with higher baseline daily insulin doses and longer duration of diabetes." (PMID 24578756, 2014). "Similarly, whole body insulin sensitivity was associated with impairments in behavioral flexibility in insulin-resistant rats that were not frankly diabetic, suggesting that insulin resistance affects cognitive ability and this precedes the development of diabetes." (PMID 24764191, 2014). "In fact, of the 2282 participants with diabetes at the initial survey, only 107 participants (4.7%) were on insulin treatment, which was confirmed by the self-reported questionnaire." (PMID 24998950, 2014).
diabetes (continued). "Defect of initial phase of insulin secretion is the earliest detectable abnormality in diabetes mellitus." (PMID 24950764, 2014). "Malin et all showed how exercise training and MET are both able to improve insulin sensitivity after 12 weeks of therapy in men and women with pre-diabetes." (PMID 24884495, 2014). "Enlarged mean SC abdominal adipocyte along with a low insulin sensitivity and acute insulin secretory response independently predicted diabetes in NGT subjects over an average follow up of about nine years." (PMID 25251402, 2014). "Given the growing prevalence of T2D and the limited availability of diabetes specialist resources, insulin initiation and titration in primary care is necessary for uncomplicated patients." (PMID 24886287, 2014). "Alterations of insulin signaling in types 1 or 2 diabetes increase tau phosphorylation and tau cleavage, promoting AD pathology." (PMID 25346723, 2014). "In contrast, accumulating evidence suggests that GPI-PLD (GPLD1) has an important role in insulin signaling and pathogenesis of insulin resistance and diabetes." (PMID 24971987, 2014). "The study shows that a 4-month treatment with add-on insulin significantly increases the outgrowth of EPC in patients with type 2 diabetes mellitus." (PMID 25300286, 2014). "The insulin/insulin-like signaling pathways are highly conserved between vertebrate and invertebrate, which is an important basis of using the B. mori to model diabetes." (PMID 25302617, 2014). "Circadian clock oscillation is altered in the hearts and livers of mice in which diabetes has been generated with streptozotocin, and can be corrected by injecting insulin to overcome insulin resistance." (PMID 24655719, 2014). "The development of a cellular therapy for diabetes requires a renewable source of human insulin-secreting cells that respond to glucose in a physiologic manner." (PMID 25009980, 2014). "According to guidelines, all patients with a confirmed CFRD diagnosis or with a diabetic OGTT and classical symptoms of diabetes should receive insulin treatment immediately." (PMID 25393021, 2014). "Abnormal zinc metabolism has been suggested to play a role in the pathogenesis of diabetes and its complications due to diminution of its role in insulin action and antioxidant capacity of cytosolic superoxide dismutase." (PMID 25598753, 2014). "Hypoglycaemia is the most common acute complication of insulin therapy in patients with type-1 diabetes mellitus." (PMID 25214204, 2014). "Apart from some emerging evidences, mechanisms by which insulin dysfunction and/or other features of diabetes such as obesity and inflammation contributes to Tau pathology are still not fully elucidated." (PMID 24574966, 2014). "Following 4 weeks of diabetes, islet insulin mRNA and protein were dramatically reduced and glucagon mRNA and protein increased." (PMID 25145789, 2014). "In patients with diabetes, insulin release from pancreatic β-cells is reduced due to altered islet structure and function." (PMID 25145789, 2014). "In the MAE-treated diabetic rats, insulin showed a significantly higher level (33%) than in the untreated diabetes." (PMID 24644381, 2014). "The observation of enhanced insulin sensitivity following adenoviral knockdown of liver NPP1 expression in a mouse model of diabetes (db/db; Lepr−/−) further supports our findings." (PMID 25368121, 2014). "Individuals with this pattern had an exponential increase in both insulin levels and beta cell function before the diagnosis of diabetes." (PMID 24523667, 2014). "This would appear to link p38δ MAPK to the pathogenesis of diabetes mellitus, a disease characterised by reduced insulin sensitivity and a decrease in insulin-producing pancreatic β cells." (PMID 25313309, 2014). "Insulin is used for the treatment of diabetes mellitus, which is characterized by the elevated glucose level (above the normal range) in the blood stream, that is, hyperglycemia." (PMID 26556194, 2014).